PRRX1 (paired related homeobox 1)
Diseases named in the same sentence as PRRX1 in open-access papers (continued):
Sharing a sentence is not in itself a finding about the gene and the disease.
craniosynostosis (6 papers, 2022 to 2025). Craniosynostosis is defined as the premature fusion of one or more cranial sutures leading to secondary distortion of skull shape resulting in skull deformities with a variable presentation. "Based on the aggregated data from the 3 craniosynostosis cohorts that we screened, the prevalence of pathogenic PRRX1 variants was 0.76% (11 of 1455)." (PMID 37154149, 2023). "In this work, we describe the identification of heterozygous LoF and deleterious missense variants of PRRX1 associated with craniosynostosis in 14 unrelated families." (PMID 37154149, 2023). "Here, we used genome and exome sequencing and targeted resequencing to demonstrate that rare PRRX1 variants are enriched in individuals with craniosynostosis." (PMID 37154149, 2023). "In contrast, all 6 of the craniosynostosis-associated homeodomain missense substitutions demonstrated abnormal localization of PRRX1, with the protein localizing to the cytoplasm in the majority of cells." (PMID 37154149, 2023). "Given the evidence that small nucleotide variants of PRRX1 are enriched in craniosynostosis, we used 2 approaches to identify further index cases with pathogenic PRRX1 variants." (PMID 37154149, 2023). "This work supports a key role for PRRX1 in cranial suture development and shows that haploinsufficiency of PRRX1 is a relatively frequent cause of craniosynostosis." (PMID 37154149, 2023). "We investigated the role of heterozygous missense and loss-of-function (LoF) variants in PRRX1 associated with craniosynostosis." (PMID 37154149, 2023). "Of the 17 individuals with deleterious variants, 3 were present within a prospective UK 18-year birth cohort of 981 affected individuals (unpublished data), indicating that PRRX1 pathogenic variants are a relatively frequent (0.3% overall) cause of craniosynostosis." (PMID 37154149, 2023). "We highlight two core genes (FGF9, PRRX1) in which variants may impact key aspects of cranial suture biology, but for the majority of the genes it is likely that craniosynostosis is a rare consequence of mutation." (PMID 36980886, 2023). "The Amber genes included three variants in PRRX1 (which contributed towards the first experimental cohort of patients with craniosynostosis and variants in PRRX1, providing substantial evidence to promote this gene to Green), one splicing variant in SMAD3 (c.206+1G>A; p. ?" (PMID 36980886, 2023). "Here, we present evidence implicating pathogenic variants of PRRX1 in craniosynostosis." (PMID 37154149, 2023). "Trio-based genome, exome, or targeted sequencing were used to screen PRRX1 in patients with craniosynostosis; immunofluorescence analyses were used to assess nuclear localization of wild-type and mutant proteins." (PMID 37154149, 2023). "It will be informative to determine the feasibility and efficacy of this heterogenous suture MSC population in treating craniosynostosis, including Axin2+, Prrx1+, Ctsk+ and CD51+;CD200+ cells." (PMID 35451466, 2022). "In humans, PRRX1 loss-of-function variants are linked to agnathia-otocephaly syndrome (MIM 202650), characterized by mandibular hypoplasia among other craniofacial defects, as well as craniosynostosis." (PMID 39257002, 2024). "The phenotype associated with PRRX1 pathogenic variants and craniosynostosis seems relatively nonspecific, with a variety of sutures fused and no diagnostic syndromic features." (PMID 37154149, 2023). "PRRX1 may link to the BMP-MSX2 signaling axis in the cranial suture, overactivity of which has previously been implicated in craniosynostosis." (PMID 37154149, 2023). "Hence, transmission of a PRRX1 variant from an unaffected parent does not exclude a causal connection in an individual with craniosynostosis." (PMID 37154149, 2023).
craniosynostosis (continued). "Given the predominance of Prrx1+ cells within the cranial suture mesenchymal cell population and their significant overlap with other suture stem cell populations, this study employed Prrx1+ cell-specific Mapk14 cKO to prevent SPC senescence and ameliorate craniosynostosis." (PMID 41390905, 2025). "In contrast to the ablation of Gli1+ cells, that of Prrx1+ cells does not result in a craniosynostosis phenotype, indicating that Prrx1+ cells of the suture are dispensable for postnatal calvarial development." (PMID 35451466, 2022).
glioblastoma (5 papers, 2016 to 2025). The most malignant astrocytic tumor (WHO grade IV). "Knockdown of PRRX1 was reported to attenuate the invasiveness and neurosphere‐forming ability of glioblastoma cell lines, including T98 and U251MG, in a serum‐containing condition." (PMID 34214250, 2022). "In glioblastoma, PRRX1 promotes propagation of GICs, as well as tumor invasion and angiogenesis." (PMID 40114375, 2025). "Since recruitment of DNMT3A by the pmx‐1b isoform of PRRX1 leads to GIC differentiation through the epigenetic regulation of PROM1 gene expression, pmx‐1b and DNMT3A are potentially interesting targets for the treatment of glioblastoma." (PMID 34214250, 2022).
hepatocellular carcinoma (5 papers, 2021 to 2024). A malignant tumor that arises from hepatocytes. "In breast, lung, or hepatocellular carcinoma, PRRX1 inhibits the self-renewal and stem cell support of tumor-initiating cells." (PMID 35530319, 2022). "In the pre-metastatic microenvironment of hepatocellular carcinoma, the expression of CXCL12 can downregulate the transcription factor Paired Related Homeobox 1 (Prrx1), thereby inducing an increase in the protein and mRNA expression of CXCR4 in hepatocellular carcinoma cells via the STAT3 pathway." (PMID 38920657, 2024).
liver fibrosis (5 papers, 2020 to 2025). "Adenoviral shRNA mediated inhibition of Prrx1 in the thioacetamide model of liver fibrosis in rats also decreased fibrotic lesions, collagen deposition and hepatic stellate cells myofibroblastic differentiation." (PMID 37261432, 2023). "PRRX1 is abnormally expressed in many diseases and is involved in tumor metastasis, bone maturation, liver fibrosis, cardiovascular diseases, and adipogenesis." (PMID 32811812, 2020). "We identified 61 liver fibrosis-associated genes (e.g., AEBP1, PRRX1 and LARP6) that may serve as a repertoire of translatable drug target candidates." (PMID 34588551, 2021). "Using rodent models of liver fibrosis, a previous study uncovered a critical role of Prrx1 in PDGF-dependent HSC migration, and an adenoviral-mediated Prrx1 short hairpin RNA (shRNA) administration reduced thioacetamide (TAA)-and CCl4-induced liver fibrosis." (PMID 34588551, 2021). "In multi-drug resistance (Mdr2) knockout mice – a liver fibrosis model that progresses to HCC in about 12 months – we observed higher Prrx1 expression in Mdr2 knockout mice than in age - matched controls and a lower expression of Prrx1 in older mice with HCC compared to the younger Mdr mice." (PMID 34496784, 2021).
lung carcinoma (5 papers, 2020 to 2024). "In the previous experiments, we established that both knocking down OLR1 and PRRX1 can weaken the supportive effect of CAFs on the growth and immune escape of lung cancer cells." (PMID 39010054, 2024). "In a clinical context, we found that the expression level of PRRX1 in tumor tissues from 48 lung cancer patients was positively correlated with poor prognosis and a reduced response to anti-PD-1 therapy." (PMID 39010054, 2024). "Other cancer types that showed high PRRX1 alteration frequency in the TCGA cohorts (e.g., cholangiocarcinoma and lung cancer), also showed similar pathway annotation patterns as observed in HCC (i.e. focal adhesion and ECM organization)." (PMID 34496784, 2021). "Alternatively, sequential induction of Snail and Prrx1 by TGFβ, followed by Prrx1‐mediated induction of miR15, which downregulates Snail, generates an equivalent binary regulatory network relevant to normal developmental and breast or lung cancer EMT." (PMID 35348275, 2022). "In lung cancer, PRRX1 knockdown inhibits the expression of Caspase 3, caspase 9, Apaf-1, and cytochrome C, leading to enhanced anti-apoptotic capacity and resistance to cisplatin in lung cancer cells." (PMID 32811812, 2020). "Knockdown of PRRX1 significantly inhibited CAFs’ function, while further overexpression of OLR1 restored CAFs’ support for lung cancer cell growth, migration, and immune evasion." (PMID 39010054, 2024). "PRRX1 promotes OLR1 expression by recruiting H3K27ac and H3K4me3, activating CAFs, and thereby promoting the growth, migration, and immune evasion of lung cancer cells." (PMID 39010054, 2024). "The PRRX1 isoform PRRX1A was found to play important roles in regulating the metastatic potential and stemness of lung cancer, a finding supported by the results of our pan-cancer analysis." (PMID 35281030, 2022). "Therefore, we hypothesized whether PRRX1 could regulate OLR1 expression through transcriptional control and promote CAF activation in lung cancer." (PMID 39010054, 2024). "In cholangiocarcinoma and lung cancer, we also observed a negative correlation with metabolic pathways, suggesting that similar functions predicted for PRRX1 in HCC may apply to other cancer types." (PMID 34496784, 2021).
lung fibrosis (5 papers, 2018 to 2025). "In conclusion, our study strongly indicates that Prrx1 loss of function in Prrx1enh-positive cells exacerbates bleomycin-induced lung fibrosis while impacting the accumulation of this specific cell population within the fibrotic lung." (PMID 40856011, 2025). "Building upon our lineage tracing findings, we proceeded to investigate the impact of Prrx1 loss of function within the Prrx1enh subpopulation in the context of lung fibrosis." (PMID 40856011, 2025). "Upon analysis, the results unveiled an unexpected outcome, indicating that Prrx1 loss of function in Prrx1enh-positive mesenchymal cells aggravated bleomycin-induced lung fibrosis in vivo." (PMID 40856011, 2025). "In summary, our results indicated that PRRX1 TFs upregulation was associated with fibrosis development in the bleomycin-induced model of lung fibrosis." (PMID 37261432, 2023). "In conclusion, our study unveils the role of the pro-fibrotic and mesenchyme associated PRRX1 TFs in lung fibrosis, involved in fibroblasts proliferation and TGF-β pathway responsiveness during myofibroblastic differentiation." (PMID 37261432, 2023). "Since Prrx1 loss of function is associated with perinatal lethality in Prrx1-/- pups, we sought first to evaluate Prrx1 function during lung fibrosis using Prrx1+/- +/- mice." (PMID 37261432, 2023). "Future studies could also explore the effects of targeting Prrx1 loss specifically in these populations, including the pro-fibrotic Lrrc5pos/ Cthrc1pos cluster, to provide a more comprehensive understanding of the role of PRRX1 in lung fibrosis." (PMID 37261432, 2023). "We previously showed that inhibiting Prrx1 using an ASO effectively attenuated bleomycin-induced lung fibrosis." (PMID 40856011, 2025). "In vivo experiments showed that global Prrx1 inhibition using a Prrx1-targeting antisense oligonucleotide (ASO) significantly attenuated fibrosis in the murine bleomycin model of pulmonary fibrosis." (PMID 40856011, 2025). "With regard to lung fibrosis, our group identified PRRX1 as a key mesenchymal TF during fibrosis development." (PMID 40856011, 2025). "In the present study, we further characterized the Prrx1-positive mesenchymal cells in the bleomycin preclinical mouse model of lung fibrosis using a lineage tracing approach with a Prrx1:CreERT2; Rosa26iTomato transgenic mouse line." (PMID 40856011, 2025). "PRRX1 mRNA expression was restricted to the fibroblast / mesenchymal lung cell lineages in either lung transplant donors or recipients with pulmonary fibrosis." (PMID 37261432, 2023). "This is the first study to evidence the critical role of the PRRX1 transcription factors in lung fibrosis pathophysiology." (PMID 37261432, 2023). "In idiopathic pulmonary fibrosis, the Paired-related Homeobox Protein (PRRX1) TF has been identified as crucially involved in eliciting a pro-fibrotic response." (PMID 38124183, 2023). "Endotracheal administration of this ASO from day 7 in the bleomycin-induced lung fibrosis model allowed us to inhibit locally and efficiently Prrx1 TFs during the active fibrosis phase in a ‘curative’ protocol." (PMID 37261432, 2023). "Overall, these data demonstrate that PRRX1 targeting in the lung has the potential to inhibit lung fibrosis development." (PMID 37261432, 2023). "The local administration of LNA-modified oligonucleotides (ASOs) targeting PRRX1, specifically to the lung via an endotracheal route, has shown effectiveness in attenuating lung fibrosis in a mouse model." (PMID 38124183, 2023). "Consistently, PRRX1 was recently identified to be involved in idiopathic pulmonary fibrosis, and inhibition of PRRX1 activity was sufficient to alleviate the development of pulmonary fibrosis." (PMID 34588551, 2021). "Also, our findings revealed a significant decrease in the count of tdTomato-positive cells following Prrx1 deletion within the Prrx1enh subpopulation in tamoxifen-treated Prrx1:CreERT2; Prrx1fl; Rosa26iTomato lungs during lung fibrosis." (PMID 40856011, 2025).
lung fibrosis (continued). "Furthermore, the effectiveness of the administration of Prrx1 ASO in the bleomycin model of pulmonary fibrosis is particularly interesting." (PMID 37261432, 2023). "Finally, inhibition of Prrx1 with LNA-modified ASO strongly impacted lung fibrosis development in in vivo and ex vivo preclinical models." (PMID 37261432, 2023). "Similarly, lineage tracing experiments in mice should be undertaken to identify the source of those Prrx1-positive mesenchymal cells during lung fibrosis development." (PMID 37261432, 2023). "PRRX1 ASO attenuates lung fibrosis in mouse and Human Precision-cut Lung slices (PCLS)." (PMID 37261432, 2023). "PRRX1 inhibition attenuates lung fibrosis in bleomycin murine model." (PMID 37261432, 2023). "While our in vitro findings in adult Human lung fibroblasts showed that PRRX1 inhibition mainly impacted ACTA2 expression levels, Prrx1 ASO treatment in the bleomycin mouse model of lung fibrosis also inhibited the deposition of ECM proteins such as Collagen 1, Fibronectin, Tenascin C, and Elastin." (PMID 37261432, 2023). "Finally, targeted inhibition of Prrx1 attenuated fibrotic remodeling in vivo with intra-tracheal antisense oligonucleotides in bleomycin mouse model of lung fibrosis and ex vivo using human and mouse precision-cut lung slices." (PMID 37261432, 2023). "The PRRX1 transcription factor (TF) has been found to be reactivated in IPF and was previously identified as a key mesenchymal TF in pulmonary fibrosis." (PMID 40856011, 2025). "To confirm the effect of the Prrx1 ASO in a second model of lung fibrosis, we took advantage of a well-established ex vivo model of lung fibrosis using precision-cut lung slices (PCLS) derived from mouse and Human lung samples." (PMID 37261432, 2023). "One should bear in mind that this experimental setup targeted both Prrx1enh-positive and Prrx1enh-negative cells within PRRX1-expressing mesenchymal populations during lung fibrosis." (PMID 40856011, 2025). "To evaluate the involvement of PRRX1 TFs in pulmonary fibrosis in vivo, we then chose to treat wild type mice with a third generation antisense LNA-modified oligonucleotide (ASO) targeting both Prrx1 isoforms by an endotracheal route to target specifically the lung." (PMID 37261432, 2023). "However, at the exception of TBX4 and PRRX1, the expression of all these other TFs is not restricted to mesenchymal lineages, which means that targeting those TFs may impact both lung fibrosis and epithelial regeneration/repair." (PMID 37261432, 2023).
bladder cancer (4 papers, 2020 to 2022). "A CT-track simple repetitive sequence was inserted into the CT-repeat region in the core promoter, caused decreased PRRX1 expression in bladder cancer." (PMID 35033028, 2022). "For instance, the correlation coefficient between PRRX1 and CD86, a co-stimulatory molecule on antigen-presenting cells that had been demonstrated to act as a pivotal role in tumor immunity in pancreatic and bladder cancers, reached 0.683." (PMID 36483329, 2022). "The remaining 5 genes have not been found to be associated with the prognosis of bladder cancer (BTBD16, OLFML2B, PRRX1, SPINK4, and SPON2)." (PMID 33204728, 2020).
liver cancer (4 papers, 2020 to 2025). An epithelial or non-epithelial malignant neoplasm that arises from the liver. "In liver cancer, downregulation of PRRX1 can promote tumors to produce stem cell-like features." (PMID 35530319, 2022). "Intriguingly, the CCA marker KRT19 and the PROX1 targets PRRX1 and PPARG exhibited a negative correlation with PROX1 expression in tumor tissue, suggesting that PROX1 could regulate liver cancer plasticity and HCC versus CCA fate." (PMID 39948437, 2025).
osteosarcoma (4 papers, 2019 to 2024). A usually aggressive malignant bone-forming mesenchymal neoplasm, predominantly affecting adolescents and young adults. "For example, ablation of Patched1, which activates the Hedgehog signaling, in Prrx1-lineage cells leads to development of osteosarcoma and chondroma whereas ablation of Patched1 in Dermo1-lineage cells fails to do so60." (PMID 38561335, 2024). "We further show that Ptch1-/-enchondromas and osteosarcomas are derived from Prrx1+ lineage located at cartilage and periosteal bone, respectively and they express limited levels of markers for differentiated chondrocytes and osteoblasts, respectively." (PMID 31482846, 2019). "Cyclopamine or GANT61 also diminished the development of osteosarcoma in Prrx1-CreERT; Ptch1f/f mice." (PMID 31482846, 2019). "This study for the first time shows that deletion of Ptch1 alone in Prrx1+ MSCs results in development of enchondromas and osteosarcomas in the same mice." (PMID 31482846, 2019). "(B) Representative presentation of osteosarcoma (OS) in forelimb (top) and hindlimb (bottom) in Prrx1-CreERT; Ptch1f/f mice 5 months after TAM injection." (PMID 31482846, 2019). "(D) Representative histological section of osteosarcoma in Prrx1-CreERT; Ptch1f/f mice 5 months after TAM injection." (PMID 31482846, 2019). "Prrx1-CreERT;Ptch1f/f mice also developed tumors at the periosteal surfaces that have features of osteosarcoma: expansive osteoid lesions with mushroom-shaped appearance that were only located at cortical bones of the limbs, which later transgressed the cortex." (PMID 31482846, 2019). "Importantly, IWP2 treatment rescued joint deformation and growth plate defects and diminished enchondroma and osteosarcoma formation of Prrx1-CreERT; Ptch1f/f mice." (PMID 31482846, 2019). "Thus, Prrx1-CreERT; Ptch1f/f mouse represents a unique model useful for dissecting the initiation and progression of both enchondroma and osteosarcoma and for testing drug candidates to target these two tumors." (PMID 31482846, 2019). "However, the function of PRRX1 in human osteosarcoma has not been determined." (PMID 35530319, 2022).